BMI1 (BMI1 proto-oncogene, polycomb ring finger)
Diseases named in the same sentence as BMI1 in open-access papers (continued):
Sharing a sentence is not in itself a finding about the gene and the disease.
pancreatic cancer (continued). "After Bmi1 knockdown, the expression of antioxidant genes including CAT, MnSOD, GSTO1, NQO1 and SOD decreased significantly in pancreatic cancer cells." (PMID 27177084, 2016). "Expression of BMI-1 and CSCs marker CD133 was assessed by using immunocytochemistry in 83 pancreatic cancer patients." (PMID 26840020, 2016). "To validate the role of ROS in the sensitization of gemcitabine after Bmi1 inhibition, we used DCFH-DA probe to detect ROS in pancreatic cancer cells." (PMID 27177084, 2016). "We then analyzed the association of expression groups (CD133-/BMI-1-, CD133+/BMI-1-, CD133-/BMI-1+ and CD133+/BMI-1+) with survival of pancreatic cancer patients." (PMID 26840020, 2016). "Bmi1 also plays an important role in both EMT and stemness processes in human nasopharyngeal and pancreatic cancers." (PMID 26023734, 2015). "Quantitative RT-PCR was performed to measure Bmi1 levels in the CSCs (cell surface markers CD44+CD24+ESA+) and compared to the remaining bulk tumor cells harvested from the human pancreatic cancer xenografts grown in NOD-SCID mice." (PMID 23437065, 2013). "In pancreatic cancer, overexpression of Bmi-1 induced activation of the P13K/Akt pathway by negative regulation of PTEN in CSCs." (PMID 36726797, 2023). "The miR-15 family regulates key stemness markers such as BMI-1 and DCLK1 in pancreatic cancer." (PMID 33562727, 2021). "Accordingly, ectopic BMI1 also abrogated significantly the induction of apoptosis promoted by SOX9 silencing, reducing by over 50% the percentage of cells with active Caspase-3 and proteolyzed PARP1 in gastric and pancreatic cancer cells." (PMID 31941916, 2020). "In this study, we develop our hypothesis that high glucose affects the expression of Bmi1, AMPK, GATA2, and MICA/B and promotes pancreatic cancer cells to escape from immune surveillance." (PMID 31088566, 2019). "Bmi1, a polycomb group (PcG) protein, was found to be up-regulated by high glucose, and mediated the inhibition of MICA/B expression through promoting GATA2 in pancreatic cancer." (PMID 31088566, 2019). "Moreover, after AMPK signaling was activated under high glucose, Bmi1 decreased, GATA2 increased and MICA/B recovered in pancreatic cancer cells." (PMID 31088566, 2019). "Moreover, pancreatic cancer patients with co-expression CD133 and BMI-1 (CD133+/BMI-1+) tended to have poorer outcomes than those with other expression combinations." (PMID 26840020, 2016). "Accordingly, gemcitabine and Bmi1 siRNA enhanced active caspase-3, active caspase-9 and cleaved poly (ADP-ribose) polymerase-1 in pancreatic cancer cells, and these enhancements could be also suppressed by NAC treatment." (PMID 27177084, 2016). "The quantification of Bmi1, Ring1b and H2AK119ub positively stained nuclei in KPC mice exhibits that tumor cells harboring high levels of these markers were greatly enriched during pancreatic cancer progression." (PMID 26716510, 2016). "In addition, overexpression of BMI-1 and CD133, taken together, will predict poor survival of pancreatic cancer patients." (PMID 26840020, 2016). "In pancreatic cancer, the EMT-activator, Zeb1, maintains stemness of cells, in part, through Bmi1." (PMID 26023734, 2015). "Despite these results, a functional role for Bmi1 has not been previously elucidated in human or murine pancreatic cancer." (PMID 23437065, 2013). "To test the in vivo relevance of the tumorsphere experiments, we implanted equal numbers of Bmi1 silenced and control lentiviral transfected CD44+CD24+ESA+ CSCs derived from primary human pancreatic cancer xenografts in the subcutaneum of NOD/SCID mice and measured the resultant tumor growth." (PMID 23437065, 2013). "A more recent study demonstrated that PCSCs had much higher expression of Bmi1 mRNA than did normal pancreatic tissue cells and marker-negative bulk pancreatic tumor cells." (PMID 24325450, 2013).
pancreatic cancer (continued). "However, low-dose VPA (0.5 mM), in combination with gemcitabine, promotes the migration and invasion of pancreatic cancer, and high-dose VPA (5 mM) enhances the sensitivity of PCCs to gemcitabine through p38 activation, which suppresses the activation of STAT3 and Bmi1." (PMID 41020871, 2025). "Furthermore, CD44V3 knockdown significantly suppressed the expression of multiple stemness markers, including BMI1, KLF4, SOX2, and NANOG, indicating that, in accordance with CD44V, CD44V3 possesses stemness-maintaining ability and then promotes pancreatic cancer migration and invasion." (PMID 36292918, 2022). "CSC target genes (CD24, EpCAM, BMI1, and LGR5) were also downregulated after JNKi treatment, suggesting that the JNK pathway might play a role in the regulation of CSCs in pancreatic cancer." (PMID 26840266, 2016). "Moreover, high glucose inhibited AMP-activated protein kinase signaling, leading to high expression of Bmi1, a polycomb group (PcG) protein which was found to be up-regulated by high glucose, and mediated the inhibition of MICA/B expression through promoting GATA2 in pancreatic cancer." (PMID 32631421, 2020). "However, the role of Bmi1 in regulating immunity in pancreatic cancer was not defined." (PMID 31088566, 2019).
head and neck squamous cell carcinoma (33 papers, 2011 to 2025). A squamous cell carcinoma that arises from any of the following anatomic sites: lip and oral cavity, nasal cavity, paranasal sinuses, pharynx, larynx, and salivary glands. "In head and neck squamous cell carcinoma (HNSCC), miR-200c suppresses HNSCC -associated cancer stem cells by targeting the 3′ UTR of BMI1, thereby reducing the tumor’s metastatic potential." (PMID 39859424, 2025). "In head and neck squamous cell carcinoma, BMI1 sustains cancer stem cell self-renewal and activates AP-1 transcription, driving metastasis and chemoresistance." (PMID 40623983, 2025). "TWIST1 upregulates BMI1, a marker of CSCs that is essential for tumor initiation capacity in head and neck squamous cell carcinomas." (PMID 38555451, 2024). "Murine leukemia virus insertion site 1 (Bmi1) was demonstrated to control self-renewal of CSCs and to function in human head and neck squamous cell carcinoma (HNSCC)." (PMID 35629138, 2022). "On the other hand, it has been shown that the activation of hsa-miR-494-3p exhibits a strong ability to reduce cancer stemness in head and neck squamous cell carcinomas by targeting Bmi1 and ADAM10, which correlates with longer survival time." (PMID 30234021, 2018). "Artemisinin, an antimalarial drug, inhibits tumor cell proliferation of head and neck squamous cell carcinomas by inhibiting Bmi1 expression." (PMID 29163356, 2017). "Here we sought to determine the therapeutic efficiency of PTC-209, a potent and selective Bmi1 inhibitor, in head neck squamous cell carcinoma (HNSCC) cells and a HNSCC xenograft model." (PMID 29200967, 2017). "Analogous studies confirmed Bmi1 expression in CD44-positive head and neck squamous cell carcinoma CSCs and in CD49f Sca-1-double positive prostate CSCs." (PMID 26770215, 2016). "Overexpression of BMI-1 in head and neck squamous cell carcinoma promote stemness properties by increasing the expression of stem cell marker and drug-resistance gene." (PMID 21851624, 2011). "The overexpression of BMI1 has been evident in head-neck squamous cell carcinoma." (PMID 35261819, 2022). "In addition, Bmi1 inhibitor PTC-209 has been proved to inhibit tumor growth by targeting CSC self-renewal in head and neck squamous cell carcinoma." (PMID 32884573, 2020). "BMI-1 has been shown to promoting EMT in head and neck squamous cell carcinoma, implies the possibility that reexpression of miR-194 may lead to a reversal of EMT phenotype of invasive EC cells." (PMID 21851624, 2011). "Notably, recent research has shown that BMI-1 plays essential roles in inducing EMT in head and neck squamous cell carcinoma." (PMID 21851624, 2011). "Furthermore, BMI1, part of the polycomb group (PcG) proteins crucial for stem cell renewal, is targeted alongside cisplatin to synergistically suppress growth in head and neck squamous cell carcinoma (HNSCC) cells." (PMID 38702734, 2024). "In head and neck squamous cell carcinoma (HNSCC), BMI1 is highly expressed in CD44+ cells that exhibit CSC features of self-renewal, differentiation, and chemoresistance." (PMID 35455671, 2022). "In the head and neck squamous cell carcinoma, treatment with the NLRP3 inhibitor MCC950 decreased sphere and colony formation as well as cancer stem cell marker BMI1, ALDH1, and CD44 expression." (PMID 38904007, 2024). "For example, it was shown that BMI1, a component of PRC1, acted cooperatively with TWIST1, one of EMT-related transcription factors (EMT-TFs), to repress CDH1 during EMT in head and neck squamous cell carcinoma." (PMID 33779563, 2021). "TWIST1 upregulates BMI1, which is essential for promoting EMT and tumor-initiating capability, in head and neck squamous cell carcinoma." (PMID 34809669, 2021). "Hypoxia-induced Twist1 directly enhances Bmi1 transcription and cooperates with Bmi1 to induce EMT and stemness properties in head and neck squamous cell carcinoma." (PMID 33014838, 2020).
head and neck squamous cell carcinoma (continued). "In head–neck squamous cell carcinoma Cal27 and FaDu cell lines, PTC-209 seems to downregulate Bmi-1 expression both at transcription and posttranslational levels." (PMID 31695609, 2019). "CD44, CD133, BMI1 and ALDH are considered frontline markers for detection of CSCs in OSCC, and other head and neck squamous cell carcinomas (HNSCCs)." (PMID 30002682, 2018). "Similar to CD24, previous studies have identified CD44, BMI1 and ALDH1 as putative markers for CSC in head and neck squamous cell carcinomas." (PMID 24612587, 2014). "In addition, the surface glycoprotein CD44 and oncogene BMI1 have been identified as key markers of the CSC subpopulation in breast cancer and head and neck squamous cell carcinoma (HNSCC)." (PMID 23300583, 2012). "A CD44-targeted virus-mimicking nanomedicine encapsulating the BMI1 inhibitor PTC209 (PTC209@VNP-HA) was designed to treat head and neck squamous cell carcinoma (HNSCC)." (PMID 40242481, 2025). "BMI1 was found to be regulated by Twist1 to promote EMT in head and neck squamous cell carcinoma (HNSCC)." (PMID 39598229, 2024). "In the context of head and neck squamous cell carcinoma (HNSCC), it was found that EMT-TF, Twist can control CSC stemness by signaling to Bmi1." (PMID 36076302, 2022). "Bmi-1, CD133, Nanog and Oct-4 have been reported as cancer stem cell (CSC) markers in head and neck squamous cell carcinoma (HNSCC)." (PMID 28220856, 2017). "Similarly, the cooperation between Twist1 and BMI1 to suppress let-7i expression promoted the acquisition of properties of the EMT, namely cell migration and stem-like properties in head and neck squamous cell carcinoma (HNSCC)." (PMID 32353968, 2020).
bladder cancer (32 papers, 2009 to 2026). "The results provided a novel insight into the portion of mechanism underlying BMI1-mediated chemoresistance in bladder cancer, presenting BMI1 as a valuable prognosis indicator and potential therapeutic target for GC-resistant bladder cancer." (PMID 34270461, 2021). "In our previous research, elevated BMI1 (B-cell specific Moloney murine leukemia virus integration region 1) expression in bladder cancer conferred poor survival and was associated with chemoresistance." (PMID 34270461, 2021). "BMI1 was highly expressed in the T24 bladder cancer cell line and it has been shown to be associated with a very poor prognosis in bladder cancer patients." (PMID 29220397, 2017). "BMI1 is a reported miR-200 target gene, and increased BMI1 expression has been associated with poor prognosis in bladder cancer patients." (PMID 26517683, 2015). "Therefore, Bmi-1 also is an oncogene, and its abnormal expression is associated with tumorigenesis and drug resistance in many cancers, including bladder cancer cells, B-cell lymphoma cells, melanoma cells, and others." (PMID 35897796, 2022). "Herein, this study uncovered a novel mechanism underlying BMI1 up-regulation and BMI1-mediated activation of P-GP in GC-chemoresistant bladder cancer, and represented this protein as a potential target for GC-chemoresistant patients with bladder cancer." (PMID 34270461, 2021). "High expression of BMI1 has been shown to be associated with poor prognosis in bladder cancer." (PMID 23820733, 2013). "Our findings suggested that BMI1 may represent a novel diagnostic marker and a therapeutic target for bladder cancer, and deserves further investigation." (PMID 23820733, 2013). "Our findings suggest that BMI1 may represent a novel diagnostic marker and a therapeutic target for bladder cancer, and deserves further investigation." (PMID 23820733, 2013). "And we found that BMI1 knockdown effectively inhibited bladder cancer T24 cells proliferation and migration in vitro, and it promoted bladder cancer invasion, maybe by causing epithelial-to-mesenchymal transition (EMT)." (PMID 23820733, 2013). "For example, miR-139-5p inhibition was shown to attenuate sodium butyrate-induced mitochondrial autophagy in bladder cancer cells by targeting Bmi-1 and reducing ROS production." (PMID 40232847, 2025). "Yan Zhang and collaborators demonstrated that betulinic acid induces autophagy-dependent apoptosis via the Bmi-1/ROS/AMPK-mTOR-ULK1 axis in human bladder cancer cells, which corroborates our results." (PMID 37111343, 2023). "Sodium butyrate induced AMPK/mTOR pathway-dependent autophagy via the miR-139-5p/Bmi-1 axis in human bladder cancer cells." (PMID 35897796, 2022). "In CC16, miR-15 has been shown to inhibit bladder cancer cell proliferation, migration and invasion in vitro by targeting BMI1 through the PI3K/AKT pathway." (PMID 36322407, 2022). "Knockdown of Bmi-1 in bladder cancer cells was shown to inhibit stemness properties and tumorigenicity of side population cells and to induce apoptosis." (PMID 34510030, 2021). "For investigating the roles of BMI1 in bladder cancer chemoresistance, we knock-downed or overexpressed BMI1 in T24 and BIU-87 cells, respectively." (PMID 34270461, 2021). "In bladder cancer, BMI1 reduction inhibits cell proliferation, migration, invasion, stemness properties and tumorigenicity." (PMID 34270461, 2021). "Analogously, BMI1 overexpression increased P-GP protein in bladder cancer cells, whereas BMI1 knockdown decreased its expression." (PMID 34270461, 2021). "Collectively, aberrant BMI1 amplification contributes to BMI1 overexpression and chemoresistance in bladder cancer, which confers poor prognosis." (PMID 34270461, 2021). "The oncogenic role of BMI1 in chemoresistance of bladder cancer deserves to be further characterized." (PMID 34270461, 2021).
bladder cancer (continued). "BMI1 overexpression dramatically promoted drug efflux, enhanced viability and decreased apoptosis of bladder cancer cells upon chemotherapy with DDP or GEM, whereas BMI1 downregulation reversed this effect." (PMID 34270461, 2021). "For further investigating the biological role of BMI1 in GC chemoresistant bladder cancer, we knock-downed BMI1 in T24/DDP&GEM cells, which was named T24/DDP&GEM-sgBMI1 cells using CRISPR/Cas9 system." (PMID 34270461, 2021). "In our previous research, elevated BMI1 expression was related to poor overall survival in bladder cancer." (PMID 34270461, 2021). "Herein, via analysis of The Cancer Genome Atlas database and validation of clinical samples, BMI1 was elevated in patients with bladder cancer resistant to cisplatin and gemcitabine, which conferred tumor relapse and progression." (PMID 34270461, 2021). "Consistently, our study revealed that BMI1 was overexpressed in GC-chemoresistant bladder cancer tissues, which confers poor prognosis." (PMID 34270461, 2021). "Of note, BMI1 expression was significantly higher in resistant T24/DDP&GEM cells than that in T24 cells, which was consistent with the elevated BMI1 expression in bladder cancer tissues of patients resistant to GC chemotherapy." (PMID 34270461, 2021). "Quantitative IHC score analysis further corroborated the elevated BMI1 expression in bladder cancer tissues from patients resistant to GC chemotherapy." (PMID 34270461, 2021). "For further investigating the regulation role of BMI1 in human bladder cancer, we firstly analysed BMI1 levels in bladder cancer tissues from TCGA-bladder urothelial carcinoma (BLCA) database." (PMID 34270461, 2021). "Overexpressing BMI1 significantly enhanced, whereas silencing BMI1 attenuated drug efflux and chemoresistance of bladder cancer cells." (PMID 34270461, 2021). "A recent study that investigated bladder cancer also indicated that Bmi-1 was the target protein of miR-139-5p." (PMID 34512152, 2021). "This research investigated the oncogenic roles of BMI1 in GC-chemoresistant bladder cancer and potential functions of miRNAs in BMI1-mediated activation of P-GP in chemoresistant bladder cancer." (PMID 34270461, 2021). "Correlation between BMI1 expression and clinicopathological characteristics of 240 bladder cancer specimens." (PMID 34270461, 2021). "Functionally, BMI1 overexpression dramatically promoted drug efflux, enhanced viability and decreased apoptosis of bladder cancer cells upon treatment with cisplatin or gemcitabine, whereas BMI1 downregulation reversed this effect." (PMID 34270461, 2021). "Several clinical trials using XR-9576 in combination with chemotherapy revealed that XR-9576 is a potent P-GP antagonist without significant side effects, representing XR-9576 as a promising treatment for MDR bladder cancer with ectopic BMI1 expression." (PMID 34270461, 2021). "miR-3682-3p directly suppressed ABCB1 gene, contributing to BMI1-mediated chemoresistance in bladder cancer cells." (PMID 34270461, 2021). "Consistently, the retention rate of fluorescent dye was elevated in T24/DDP&GEM-sgBMI1 cells as detected by flow cytometry, which suggested that BMI1 mediated chemoresistance of bladder cancer probably via promotion of drug efflux." (PMID 34270461, 2021). "BMI1 was detected to be over-expressed in bladder cancer specimens from GC-chemoresistant patients, which was consistent with the elevated BMI1 expression in established GC-resistant T24/DDP&GEM cells." (PMID 34270461, 2021). "BMI1 expressions in bladder cancer tissues were inversely related to relapse-free survival (P < 0.001) and progression-free survival (P < 0.001)." (PMID 34270461, 2021). "In our previous research, elevated BMI1 expression in bladder cancer was correlated with poor overall survival." (PMID 34270461, 2021). "Taken together, BMI1 upregulation in bladder cancer involves in chemoresistance and is related to poor prognosis for bladder cancer." (PMID 34270461, 2021).